ENSG00000207502
Synonyms: LOC124900438
Gene: Small nucleolar RNA gene on chromosome 1 (115,621,872 to 115,622,005, reverse strand). Ensembl gene ENSG00000207502.
Gene Ontology:
Biological process: RNA processing
Cellular component: nucleolus
Homologues: Paralogues in human: SNORA80E (81% identical), SNORA80A (73% identical), SNORA80B (71% identical), SNORA80C (69% identical), SNORA80D (69% identical).